IL13 (interleukin 13)
Diseases named in the same sentence as IL13 in open-access papers (continued):
Sharing a sentence is not in itself a finding about the gene and the disease.
eosinophilia (continued). "Eosinophilia remains one of the treatable traits; recent trials with anti–IL-4/IL-13 therapies have shown improved exacerbation outcomes in tobacco-related COPD." (PMID 40959786, 2025). "Within the ILC family, group 2 ILCs (ILC2s), in particular, contribute significantly to type 2 inflammation through their rapid production of cytokines such as IL-5 and IL-13, promoting airway eosinophilia and airway hyperreactivity." (PMID 40355861, 2025). "While our data suggest that IL-13 alone may have limited diagnostic value due to its weak correlations with other Th2 markers and clinical parameters, its role in specific subgroups—such as patients with marked eosinophilia—or in combination with other biomarkers merits further investigation." (PMID 41002723, 2025). "Mechanistically, allergen-sensitized Th2 cells produce pro-inflammatory cytokines such as IL-4, IL-5, and IL-13, thereby driving airway eosinophilia and chronic inflammation." (PMID 41422349, 2025). "Corticosteroids and specific biological agents have demonstrated positive results in mitigating sputum eosinophilia, while drugs targeting IL-13 have shown inconsistent outcomes." (PMID 38474348, 2024). "When activated by the alarmins or lipid mediators in vivo in mice, ILC2s can drive tissue eosinophilia independently of functional T cells, reflecting their potent productions of IL-5, IL-9, GM-CSF, IL-13, and, in some contexts, IL-4." (PMID 40047886, 2024). "Th2 cells produce cytokines such as IL-4, IL-5, and IL-13, which are pivotal in promoting IgE synthesis and subsequent histamine release (IL-4 and IL-13), eosinophilia (IL-5), and mucus oversecretion, airway hyperresponsiveness, and remodeling (IL-13)." (PMID 39770422, 2024). "Although the major effects of IL-13 are very similar to those of IL-4, some independent pathways of eosinophilia and M2 macrophage polarization have been reported for IL-13." (PMID 39720728, 2024). "Two independent studies demonstrated that IL-13 was necessary and sufficient to elicit airway eosinophilia, goblet cell metaplasia, collagen deposition, and AHR to methacholine in mice." (PMID 40047886, 2024). "The authors also showed that by depleting IL-13-producing cells (which include ILC2s) in mdx at 4 weeks of age, IL-5 levels were decreased and muscle eosinophilia was diminished, suggesting that IL-13 is required for eosinophil infiltration." (PMID 38585275, 2024). "Administration of the LGG strain in other studies led to a reduction in airway hyperresponsiveness (AHR) and eosinophilia, as well as a decrease in the concentrations of IL-5 and IL-13." (PMID 39796449, 2024). "In the GSE36830 dataset, it is stated that polyp tissues from CRSwNP patients have significantly increased expression of ECP, IL-5, IL-13, and Eotaxin-1, 2, and 3 compared to normal tissues, indicating eosinophilia." (PMID 38975344, 2024). "We also observed a reduction in IL-5 and IL-13-expressingILC2s and T effector cells, whichwas associated with decreased BAL and lung eosinophilia, and reductions in type 2-polarizedCD11b+ DCs and M2 macrophages." (PMID 38935708, 2024). "Deposition of HA in the alveolar epithelium correlated with regions of damaged tissue and the type 2 immune response, which is characterized by eosinophilia and increased type 2 cytokines such as IL‐13." (PMID 39606183, 2024). "In contrast, untreated mice and those treated at day 7 after infection showed lower Th1 responses and robust Th2 responses (IL-5- and IL-13-producing T cells and increased eosinophilia)." (PMID 36719231, 2023). "For instance, Interleukin-5 (IL-5) is essential for airway eosinophilia, and Interleukin-4 (IL-4) and Interleukin-13 (IL-13) are necessary for Immunoglobulin E (IgE) production." (PMID 37781715, 2023). "In the T2 endotype, there is an increase in the production of Th2 cytokines, including interleukin-4, interleukin-5, and interleukin-13, high levels of immunoglobulin-E in polyp tissue, and eosinophilia." (PMID 37674852, 2023).
eosinophilia (continued). "ILC2s and a subpopulation of CD4+ T cells known as Th2 cells can secrete IL-4, IL-5, and IL-13 and stimulate type 2 immunity with high IgE antibodies and eosinophilia." (PMID 37152304, 2023). "This also reduced their expression of Gata3, Il4, Il5, and Il13 in lung conventional CD4+ T cells: these effects markedly reduced the eosinophilia and AHR." (PMID 37917548, 2023). "CD4+ T cells show Th2 skewing and production of IL-4, IL-5, IL-13, contributing to the atopic phenotype seen in these patients of eczema and eosinophilia." (PMID 37727514, 2023). "Other investigators have also documented the importance of IL-13/IL-4 in A. fumigatus-induced pneumonia and eosinophilia in ABPA and cystic fibrosis." (PMID 38983617, 2023). "CRSwNP patients characterized by eosinophilic inflammation and type 2 inflammation have high levels of immunoglobulin (Ig) E, interleukin (IL‐5), IL‐4 and IL‐13 in local tissues, often accompanied by eosinophilia in peripheral blood." (PMID 36840493, 2023). "These cells are responsible forinterleukin (IL) 4, IL-5, IL-9, and IL-13 as well asabnormal immunoglobulin production, i.e., atopy,eosinophilia, and mast cell enlargement." (PMID 37345397, 2023). "IL-5 promotes eosinophilia, and IL-4 and IL-13 enhance the production of eosinophil chemoattractants (CCL11/eotaxin-1, CCL24/eotaxin-2, and CCL26/eotaxin-3) and activate B cells, macrophages, fibroblasts, epithelial cells, and goblet cells." (PMID 37674852, 2023). "IL-13-driven eosinophil infiltration of the esophagus induced eosinophilia and eotaxin-1 expression in a STAT6-dependent and MID-1-dependent manner." (PMID 38026128, 2023). "This suggests that the airway eosinophilia we observed in WT mice was probably driven by IL-13 and IL-4 resulting in a less overall severe eosinophilic pathology to infection, and suggesting other cell types contributed to the immunopathology observed." (PMID 37795093, 2023). "TSLP, IL-5, IL-13 and IL-25 are the major proinflammatory cytokines that mediate eosinophilia-dominated type-2 inflammation." (PMID 37377967, 2023). "In this case of persistency of airway eosinophilia, it would be appropriate to consider a change of biologics toward blocking the IL-4/IL-13 pathways." (PMID 35055384, 2022). "Th2 cytokines such as IL-4, IL-13, and IL-9 promote eosinophilia by regulating local IL-5, eotaxin synthesis, and/or inhibiting IFN-gamma production." (PMID 35805534, 2022). "While neutrophilia was promoted, depletion of ACh also prevented the characteristic eosinophilia associated with Alternaria exposure, most likely due to restricted ILC2 activation and release of IL-13 and IL-5." (PMID 35711456, 2022). "Th2 cytokines, such as IL-4, IL-5, and IL-13, directly or indirectly promote eosinophilia by influencing eosinophil differentiation, survival, and activation." (PMID 36362100, 2022). "These cells produced large amounts of IL-5 and IL-13 and induced early eosinophilia in the lung when encountering the second nematode." (PMID 36466877, 2022). "Here, L. lactis‐EVs significantly reduced eosinophilia (IL‐5‐mediated) and mucus production (IL‐13‐mediated) in allergic asthmatic mice by enhancing Th1 immune response." (PMID 35344296, 2022). "Peripheral eosinophil counts were particularly high in this study and as for IL-13, peripheral eosinophilia was also correlated with disease severity." (PMID 36326393, 2022). "It is upregulated by type-2 cytokines like IL-4 and IL-13 and correlates with other type-2 biomarkers such as FeNO, sputum eosinophilia, blood eosinophilia, and total IgE." (PMID 36326393, 2022). "T-bet deficiency thus underlies the excessive production of Th2 cytokines, particularly IL-5 and IL-13, by CD4+ αβ T cells, causing blood eosinophilia and UAI." (PMID 35909394, 2022).
eosinophilia (continued). "For example, ILC2s are enriched in nasal polyps of chronic rhinosinusitis patients along with elevated IL5 and IL13 transcripts, suggesting an ILC2-dependent contribution to the disease-associated eosinophilia and chronic airway inflammation." (PMID 35359972, 2022). "ILC2s produce large amounts of IL-5 and IL-13 in response to activation with IL-33, resulting in eosinophilia and this has been adopted as a robust model for innate induction of airway inflammation." (PMID 35711456, 2022). "In contrast, depletion of ACh inhibited Alternaria-induced activation of ILC2s, suppressing the expression of IL-5, IL-13, and subsequent eosinophilia." (PMID 35711456, 2022). "IL-5 produced by lung-derived ILC2s can drive eosinophilia while IL-13 can stimulate hepatic stellate cells and induce upregulation of fibrosis-associated genes including Col1a1, Acta2 and Timp1, thus promoting liver fibrosis." (PMID 34305911, 2021). "Together, these results show that IL-13 is required for the full induction of airway eosinophilia after N. brasiliensis infection." (PMID 34127548, 2021). "IFN-γ, IL-4, and IL-13 concentrations in the airways were similar between WT and Bcl6ΔCD4 mice, as was eosinophilia; however, airway NK cell frequencies were elevated in Bcl6ΔCD4 mice compared with controls." (PMID 34665220, 2021). "We found that IL-13 was required for the full induction of airway eosinophilia and for limiting lung injury, independent from the other type 2 cytokines IL-4 and IL-5." (PMID 34127548, 2021). "Type-2 immunity is characterised by interleukin (IL)-4, IL-5 and IL-13, eosinophilia, mucus production, IgE, and alternatively activated macrophages (AAM)." (PMID 32457448, 2021). "These responses are accompanied with the induction of cytokines such as IL-4, IL-5, IL-13, and enhanced eosinophilia, and IgE responses." (PMID 34368662, 2021). "As Il5 mRNA levels were unaffected by Ruxolitinib, yet eosinophilia was greatly reduced in SA+R mice, our observations suggest that both IL-4 and IL-13 drive eosinophilic inflammation in the lung." (PMID 34777398, 2021). "Cytokines secreted by Th2 cells include IL-4, IL-5 and IL-13, which facilitate the isotope switching of antibodies, mucus secretion and eosinophilia." (PMID 34295337, 2021). "Several asthmatic features, such as airway hyperresponsiveness, eosinophilia, mucin deposition, and IL-5/IL-13 production in the lungs were decreased in the rAAV-CD39-treated mice." (PMID 34201190, 2021). "CD40 signalling is important for OVA-induced eosinophilia and the production of IL-4, IL-5, and IL-13 in a mouse model of allergic asthma." (PMID 33976586, 2021). "Our study reinforces these earlier findings but also reveal a crucial protective role for IL-13 in limiting acute lung injury, promoting airway eosinophilia, and inducing type 2 effector proteins." (PMID 34127548, 2021). "In mice, the cleaved form of IL-33 is more potent to induce secretion of IL-5 and IL-13 by ILC2s and IL-6 and IL-13 by MC/9 mast cells than IL-33FL and leads to increased eosinophilia in lungs and BALF." (PMID 34484177, 2021). "Since IL-4, IL-5, and IL-13 promote airway eosinophilia, mucus overproduction and bronchial hyper-responsiveness, it is likely that hBD-2 improves lung resistance indirectly by lowering those cytokines in the lung." (PMID 33717182, 2021). "Both papain and IL-33 have been shown to induce ILC2-dependent IL-5 and IL-13 production and airway eosinophilia." (PMID 34194431, 2021). "This type 2 immune response in CRSwNP is supported by the elevation of ILC2, the increased presence of tissue eosinophilia, a clear upregulation of IL-4, IL-5, IL-13, and local IgE, and profound tissue eosinophilia independent of atopy." (PMID 35387015, 2021). "The early over-expression of specific cytokines by ILC2 can lead to eosinophilia (IL-5), mucus production (IL-13) and lung remodeling (amphiregulin, AREG)." (PMID 33953732, 2021).
eosinophilia (continued). "IL13 is a central mediator of allergic asthma and its blockade in mice reduces eosinophilia and airway remodeling in response to HDM." (PMID 34440118, 2021). "Th2 cytokines are involved in CTCL pathogenesis of pruritus and include IL-4, IL-5 and IL-13, together with eosinophilia and IgE." (PMID 34118946, 2021). "The F1 neonates of maternal DEHP-exposed mice developed more severe allergic lung inflammation after OVA sensitization and challenge, including predominant eosinophilia and higher levels of IL-4, IL-5, and IL-13 in the BALFs, than the control F1 neonates." (PMID 33424850, 2020). "Ovalbumin (OVA)-induced allergic mice showed eosinophilia and increased T helper type 2 (Th2) cytokines including interleukin (IL)-4 and IL-13 in bronchoalveolar lavage fluid with airway hyperresponsiveness (AHR)." (PMID 33217964, 2020). "IL-5 and IL-13 have been reported to stimulate eosinophil activation and induce eosinophilia and ciliated epithelial cell hypertrophy in the respiratory tissue." (PMID 32132898, 2020). "In allergic asthma, the inflammatory process is initiated by Th2 cells that produce cytokines, such as IL-4, IL-5, IL-9, IL-13, leading to the production of IgE, eosinophilia, and goblet cell hyperplasia." (PMID 32292784, 2020). "As both IL-4, and IL-5 mRNA levels are unaffected by CD2 deficiency, yet eosinophilia was greatly reduced in HDME-treated Cd2−/− mice, our observations highlight the importance of IL-13 as the central regulator of HDME-induced lung inflammation." (PMID 32477356, 2020). "Again, HpARI suppressed type 2 immune responses while HpARI_CCP1/2 increased BAL eosinophilia, IL-5 and IL-13 production." (PMID 32695116, 2020). "In studies of the immunomodulatory function of ESPs, helminths have been shown produce ESPs to induce the generation of Th2 cytokine (IL-4, IL-10, and IL-13) by the host, inflammation, and the elevation of IgE and eosinophilia levels in the serum." (PMID 32479527, 2020). "Our flow cytometry results revealed that the effects of PGT on reducing OVA-induced eosinophilia are closely related with regulating the levels of IL-5 and IL-13 in the lung." (PMID 33374657, 2020). "Peripheral blood of chronic asthmatic patients shows elevated levels of IL-5- and IL-13- producing ILC2s, which is paralleled in patient airways by increases in IL-33 and eosinophilia." (PMID 32079296, 2020). "To date, the presence and degree of type 2 inflammatory responses, involving eosinophilia and increased levels of the proinflammatory cytokines IL-4, IL-5, and IL-13, have been the focus of asthma research." (PMID 33101299, 2020). "Anti-ICAM-1-treated mice showed lower lung ILC2s, lower BAL eosinophilia associated with a decrease in ILC2-dependent IL-5 and IL-13 expression compared to controls." (PMID 33193309, 2020). "Whole-body genetic deletion of IL-33 results in impaired clearance to N. brasiliensis in mice, which corresponds to reduced IL-13 production by ILC2s and, subsequently, reduced Relm-β production and eosinophilia." (PMID 31072011, 2019). "The immune response of sheep against GIN infections is primarily associated with the adaptive Th2-polarized profile, with local release of the interleukins IL4, IL5, and IL13, in addition to IgE production, eosinophilia, and mastocytosis." (PMID 31815153, 2019). "Treatment also reduced airway eosinophilia, AHR, allergen‐specific IgE and was associated with reduced concentrations of IL‐13 in the lungs." (PMID 30220084, 2019). "The increased levels of IL-4/IL-13 and serum IgE as well as mast cell accumulation, led us to predict the occurrence of eosinophilia." (PMID 30654796, 2019). "The exposure to IL-13 induces airway hyper-responsiveness, acute eosinophilia, and IgE and mucus production." (PMID 30126769, 2019).
eosinophilia (continued). "In a novel mouse model of non-allergic asthma overexpression of the activator protein-1 (AP-1) subunit Fra2, caused airway inflammation with IL-13 overexpression, BAL eosinophilia, mucus hyperproduction, AHR, and peribronchial collagen deposition." (PMID 31866859, 2019). "Administration of AZD8848 directly to the lung has previously been shown to inhibit eosinophilia and IL-13 levels for up to 4 weeks post-treatment following ovalbumin challenge in the Brown Norway rat." (PMID 31856838, 2019). "These alarmins are known to be natural triggers and enhancers of the Th2 type immune response, resulting in local and systemic induction of IL4, IL5, and IL13 synthesis, eosinophilia, and high levels of IgE." (PMID 31815153, 2019). "Since measuring IL-13 levels in paraffin embedded tissue biopsies is erroneous, we used eosinophilia as a marker for elevated IL-13 tissue concentrations instead." (PMID 31262043, 2019). "Directly inhibiting miR-155 expression in TH2 cells prevents TH2-mediated airway allergy (airway eosinophilia, IL-13 production and airway mucus production)." (PMID 31805682, 2019). "While this work does not definitively show a necessary role for ILC2s in clearance, it suggests that these cells are important for IL-5, IL-13, and amphiregulin production and coordination of eosinophilia in the lung during infection." (PMID 31072011, 2019). "Oral administration of 100 mg/kg extract caused 86% inhibition of eosinophilia, reduction of TH2 cytokines (IL-4, IL-5, IL-13) and TNF-α level in BALF and decreased serum IgE level in ovalbumin-sensitized mice." (PMID 31275149, 2019). "Here we conducted a thorough characterisation of the inflammatory infiltrates in the lungs of these mice and found predominant eosinophilia and Th2 inflammation with high levels of the effector cytokine IL-13." (PMID 30233597, 2018). "Dupilumab, a targeted therapy against IL-4R-alpha that modulates the IL-4/IL-13 pathway, improved asthma control and lung function in asthmatic patients with sputum eosinophilia (≥3%) or blood eosinophilia (≥300/μL)." (PMID 30598830, 2018). "IL-33 initiates allergic inflammation by activating innate lymphoid cells type 2 (ILC2s) to produce large amounts of Th2 cytokines IL-5 and IL-13 responsible for eosinophilia and IgE-class switching, respectively." (PMID 29416104, 2018). "A study shows in a model of lung inflammation that key type 2 cytokine IL-4 derived from basophils enhances ILC2 secretion of IL-5 and IL-13, ultimately favoring eosinophilia." (PMID 30524437, 2018). "Eosinophilic asthma is characterized by Th2 cell activation, IL-4, IL-5, and IL-13 production, high IgE levels and strong eosinophilia." (PMID 30534125, 2018). "Th2 cells migrated to the lung secrete the prototypical Th2 type cytokines IL-4, IL-5, and IL-13, resulting in goblet cell hyperplasia, bronchoconstriction, and eosinophilia in the airway." (PMID 29991953, 2018). "T-helper 2 (Th2) associated responses, such as production of interleukin 33 (IL-33), (interleukin 13) IL-13, (interleukin 4) IL-4 cytokines, and eosinophilia, are generally considered to be detrimental." (PMID 29463005, 2018). "In the absence of a hematological malignancy, the Th2-type cytokine interleukin-5 (IL-5) is critical for the development of a peripheral eosinophilia whilst B lymphocyte class-switching to IgE synthesis is dependent on the Th2-type cytokines IL-4/IL-13." (PMID 28506264, 2017). "These subgroups were different with respect to their expression levels of IL-5 and IL-13 within the airway, airway hyper-responsiveness, IgE, blood and airway eosinophilia, and reticular basement membrane thickness." (PMID 29018800, 2017). "In response to viral challenge, IPS-1−/− mice developed a type-2 inflammatory response as indicated by a significant eosinophilia and lymphoplasia, together with increased production of IL-5 and IL-13 in bronchoalveolar lavage fluid (BALF)." (PMID 28539639, 2017).